AR (androgen receptor)
Diseases named in the same sentence as AR in open-access papers (continued):
Sharing a sentence is not in itself a finding about the gene and the disease.
tumor (continued). "For instance, PARP1, supporting the transcription of androgen receptor in androgen receptor-positive prostate carcinoma, is necessary for tumor cell proliferation." (PMID 28991194, 2017). "To address the question of how GR expression is silenced in localized prostate cancer, we turned to a set of matched tumor/normal primary clinical samples whose AR ChIP-seq profiles were recently characterized." (PMID 28891793, 2017). "Published studies focusing on the correlation between AR expression and tumor metastasis in TNBC remain controversial." (PMID 28583190, 2017). "Using single-cell RNA-seq, we confirmed the high level of transcriptome heterogeneity in TNBC tumour cells, which included signatures for basal, immunomodulatory, luminal androgen receptor, mesenchymal or stem-like gene expression." (PMID 28474673, 2017). "Immunohistochemical (IHC) and TUNEL analyses were used to analyse the level of COX-2, PAS, AR, and Bcl-2 expressions and we observed the apoptosis of tumour cells in both model, and treatment, groups." (PMID 28383015, 2017). "Whilst that study did not specifically compare AR positive versus AR negative UGM, it did demonstrated the importance of stroma in early stage cancer, and the potential role of stromal AR signalling in tumour formation." (PMID 28117763, 2017). "In the in vitro cell culture model, the LAR subtype was shown to depend on AR signaling, as elimination of AR greatly decreased cell viability and tumor growth." (PMID 29069872, 2017). "They reported sporadic reactivity for AR, cytokeratin and EpCAM and suggested rare, undifferentiated clones from the donor tumour had established the xenograft." (PMID 29145505, 2017). "Initially, the tumor responds to therapies that mainly consist in androgen ablation, but it eventually becomes androgen resistant due to alterations in androgen receptor expression or related signalling." (PMID 26700622, 2016). "Curcumin suppressed CBP and p300 occupancy at sites of AR function through reducing histone acetylation and altering the chromatin landscape, thus reducing tumor growth and delaying the onset of castrate-resistant disease." (PMID 27529277, 2016). "Because AR and ER share similar ChIP-seq binding profiles, it was concluded that in the presence of ER, AR interacts with estrogen response elements, thereby blocking the expression of downstream estrogen target genes and inhibiting ER-stimulated tumor growth." (PMID 27285752, 2016). "In an exploratory analysis evaluating tumor GR and AR expression, we observed that tumors with strong GR expression were typically AR-negative, and tumors with strong AR expression were typically GR-negative." (PMID 27386391, 2016). "In contrast, during carcinogenesis the function of AR signaling is altered from tumor suppressive to tumor promoting." (PMID 27036029, 2016). "Conversely, levels of AR-V7 and full-length AR were significantly higher in tumours that displayed an increase in AR gene copy number compared with tumours that displayed a single AR gene copy." (PMID 27897170, 2016). "The association of loss of AR with increasing cancer aggressiveness in these studies suggests a tumor suppressor role for AR in RCC, yet two recent studies found that increased expression of AR mRNA associated with poor prognosis." (PMID 26814892, 2016). "Positive immunostaining of transgenic AR protein was observed in the majority of tumor cells of the transgenic mice, providing a link between transgenic AR expression and oncogenic transformation." (PMID 26862755, 2016).
tumor (continued). "AR-GSRs occur in the context of copy-neutral and amplified AR and display heterogeneity in breakpoint location, rearrangement class and sub-clonal enrichment in tumours within and between patients." (PMID 27897170, 2016). "Regarding the association between AR and CD90 expression and the disease status, we found that a higher CD90 staining score (score 6~8) is associated with larger tumor size." (PMID 27340775, 2016). "To test this scenario further, we next focused on subject C-12, where two tumour sites harboured a series of shared and exclusive AR deletion and duplication events, several of which were highly enriched in the tumour sub-clonal architecture." (PMID 27897170, 2016). "In a pre-clinical assay, PCa cells chronically exposed to 5-aza-2′-deoxycytidine for 21 days, exhibited a marked decrease in tumor cell proliferation and AR reactivation, with concomitantly increased PSA protein levels." (PMID 27651838, 2016). "The expression of AR has been demonstrated to increase with increasing tumour grade and stage, as does the serum levels of prostate specific antigen (PSA), the product of the proto-typical androgen responsive gene KLK3." (PMID 27120785, 2016). "Tissue samples of recurrent tumours were obtained from eight patients, and AR expression was confirmed in only two cases." (PMID 26757422, 2016). "AR expression was higher in post-menopausal women (post- vs. pre-menopausal 26.9% vs 13.4%, p < 0.001), grade 1-2 tumor (Grade 1-2 vs. 3, 40.8% vs. 23.0%, p < 0.001) and patients with axillary LN metastases (LN+ vs. LN-, 28.8% vs. 22.6%, p < 0.01)." (PMID 27374089, 2016). "Protein expression of AR is increased in recurrent tumor samples compared to paired androgen-sensitive samples in multiple isogenic tumor xenograft models." (PMID 27487144, 2016). "The diagonals of these heatmaps revealed strong signals for canonical AR mRNA splicing events in both tumours." (PMID 27897170, 2016). "The androgen receptor (AR) is a ligand-inducible transcription factor of the nuclear hormone receptor superfamily that plays a critical role in tumor initiation, growth, and progression of PCa." (PMID 26657335, 2016). "Taken together, the expression pattern of MLPH points toward a tumor‐suppressive function of MLPH, which is weakened in the presence of a rs11891426:T>G risk G allele by attenuation of androgen and AR‐regulated expression of MLPH." (PMID 26411452, 2016). "Studies with the new anti-androgen agent MDV3100 (enzalutamide) indicate that one of the ways it inactivates AR nuclear activity in tumor cells is by preventing nuclear translocation." (PMID 27028864, 2016). "Consistent with this possibility, both metformin, which activates AMPK and also inhibits fatty acid synthesis in an AMPK-independent manner, and a novel AMPK activator (MT 63-78) led to improved anti-tumor effects when combined with AR antagonists." (PMID 27248322, 2016). "Knockdown of GR prior to implantation inhibited xenograft tumor growth, establishing that GR expression is required for survival of this LNCaP AR/GR-overexpressing cell line in the presence of enzalutamide." (PMID 27487144, 2016). "Here we define diverse AR genomic structural rearrangements (AR-GSRs) as a class of molecular alterations occurring in one third of CRPC-stage tumours." (PMID 27897170, 2016). "In an ex vivo culture assay, treatment of hormone-naïve primary PCa tissue with bicalutamide and CHKAi decreased AR expression in tumor epithelia while both anti-androgens and CHKAi increased levels of cleaved caspase-3, a marker of apoptosis." (PMID 26657335, 2016). "Our present results suggest that miR-203 serves as a tumor suppressor, whereby AR activates miR-203, and the induction of miR-203 reduces SNAI2 levels." (PMID 27028864, 2016). "In contrast, subsequent studies reported that CD133+ tumor-initiating cells express AR, as assessed by dual variable flow-cytometry." (PMID 26506594, 2016).
tumor (continued). "Meta-analysis revealed a systematic decline in the expression of a previously identified benign prostate androgen-regulated gene set with increasing tumour grade, reaching significance in nine of 25 genes tested despite increasing AR expression." (PMID 27120785, 2016). "Although primary PCa is mostly an androgen-responsive tumor, the castration-resistant phenotype (CRPC) eventually emerges, and several mechanisms have been implicated, including heterogeneous loss of AR expression and aberrant promoter methylation." (PMID 27323813, 2016). "Adding AR to the 769-P cells led to increased tumor sizes and masses compared with the control group." (PMID 27848972, 2016). "Consistent with this, targeting of HSPs in preclinical models inhibits AR function and tumor growth." (PMID 26657335, 2016). "Di Marzo's group found that cannabis extracts enriched with CBD effectively decreased tumor growth in androgen receptor positive LNCaP xenografts but potentiated tumor growth of androgen receptor negative DU-145 xenografts." (PMID 27774065, 2016). "Tumor pathology was reviewed and tissue microarray sections were immunostained for androgen receptor and PD-L1." (PMID 28721372, 2016). "Expression of AR was also analyzed by immunohistochemistry, which showed increased AR expression in both the nucleus and cytosol of tumor cells grown in castrate mice." (PMID 27748439, 2016). "AR+ patients tended to have lower tumor grade (p< 0.001), but more lymph node metastases (p < 0.01)." (PMID 27374089, 2016). "These tumours have a clinically aggressive behaviour, lack AR expression, and are refractory to androgen-deprivation therapy (ADT)." (PMID 26924072, 2016). "PCa cells that lack AR apparently function as a source of tumor renewal, as these cells have stem cell characteristics and are resistant to hormonal therapy and chemotherapy." (PMID 26734997, 2016). "In the present study, we demonstrated that cyclin D1 governs the tumor phenotype and participates in determining radioresistance of PCa cells independently by androgen receptor expression." (PMID 26689991, 2016). "Here, we established a central role for KLF4 in tumor suppression by connecting its regulation by AR and modulation of miR-1 expression." (PMID 27991915, 2016). "Treatment of a CRPC patient-derived xenograft, MDA-PCa-133 expressing H874Y AR mutant with VT-464, reduced the increase in tumor volume in castrate male mice more than twice as much as the vehicle (P < 0.05)." (PMID 27748439, 2016). "Expression analysis of total tumor RNAs showed that expression of both the full-length AR and AR-V7 were significantly higher in castrate mouse tumors than in noncastrate mouse tumors." (PMID 27748439, 2016). "AR expression as a predictor of better prognosis seen in the present study appears to be contrary to the tumor promoting effect of AR signals in BC." (PMID 26885620, 2016). "This compound potentiated radiotherapy for tumor growth suppression (in vitro and in vivo) and increased the anti-proliferative and the apoptotic effects of anti-androgen therapy leading to AR downregulation." (PMID 27651838, 2016). "Microarray-based mRNA expression levels confirmed higher expression of IRS1, IGF2, IGF1R and AR in “NFκB off” compared to the “NFκB on” tumours in all five datasets." (PMID 26943587, 2016). "Our work establishes AR-GSRs as new class of AR gene alteration occurring in one third of CRPC-stage tumours." (PMID 27897170, 2016). "In primary ER-negative breast cancer, the prevalence of AR expression has ranged from 10% to 32%,20,21 likely reflecting differences in techniques as well thresholds for considering a tumor AR+ (i.e., ⩾1% vs. >10% of cells staining)." (PMID 28721372, 2016). "Persistent expression of AR and its restored activation by de novo synthesized tumor tissue androgens are among the major triggers of disease progression to metastatic castration resistant prostate cancer (mCRPC)." (PMID 27557496, 2016).
tumor (continued). "The efficacy of BAY 1024767 was further evidenced in the syngeneic Dunning R3327-G rat model with high AR expression where a significant anti-tumor effect was observed." (PMID 26760770, 2016). "CXCL12/CXCR4 transactivates members of growth factor receptor in PC cells, and expression of HER2 in PC patients correlates with tumor cell proliferation and activates androgen receptor signaling in advanced disease." (PMID 27809841, 2016). "The expression of Lin28A, AR, and Ki67 in xenograft tumor was detected by using immunohistochemistry." (PMID 27494865, 2016). "This tumor growth suppression is one of the most important downstream mechanisms regulated by the androgen-dependent activity of the AR." (PMID 27374083, 2016). "In this scenario, differential AR gene copy number profiles would be expected for the two distinct tumour sites as a result of differential enrichment of these sub-clones." (PMID 27897170, 2016). "Despite AR gene amplification, levels of full-length AR and AR-V7 mRNA in tumour C-12A were low relative to tumour C-12B and to all other tumours in this cohort." (PMID 27897170, 2016). "In summary these results demonstrate the context dependent function of the AR, and that epigenetics and/or availability of cofactors greatly influence the AR transcriptome and ultimately if AR acts in a tumor suppressive or oncogenic manner." (PMID 27378372, 2016). "The most common documented alterations in the AR pathway in CRPC, occurring in ∼60% of tumours, are amplification or mutation of the AR gene." (PMID 27897170, 2016). "In our study, AR increased EC proliferation and recruitment to the tumor microenvironment and promoted RCC progression." (PMID 27848972, 2016). "Statistical relationships were examined between AR protein expression, tumor status, and patient characteristics." (PMID 29083379, 2016). "Altogether, the results indicate that MDA-PCa-133 tumor growth in castrate mice was due to increased expression of AR and its ligand-independent isoform AR-V7, as well as CYP17A1, which is required for intratumoral testosterone biosynthesis." (PMID 27748439, 2016). "The major observation that needs to be further investigated is the ability of ID4 to revert the oncogenic AR in PCa back to normal AR activity which appears to be that of a tumor suppressor." (PMID 27487149, 2016). "In this current study, we combined clinical datasets containing genome-wide expression profiles and patient prognosis data with our RNAi screen candidates to reveal new AR co-regulators that promote AR activity during tumor progression." (PMID 27363033, 2016). "Consistent with a proposed switch in the AR driven transcriptional program with local tumour progression, we observed a consistent increase in the expression of a number of these genes in higher-grade tumours, particularly CDK1, UBE2C, CDC20 and CCNA2." (PMID 27120785, 2016). "Taken together, our study identifies novel cooperative mechanisms involving PIP5K1α, AR-V7, CDK1 and AR, which drive tumor progression and contribute to enzalutamide resistance." (PMID 27588408, 2016). "We find the androgen receptor and tumor suppressors, Nkx3.1 and PTEN, together define a transition from early to late stage disease in the TRAMP mouse." (PMID 27634876, 2016). "There is a need, therefore, to study the deregulated AR signaling in fusion gene‐positive PCa tumor cells." (PMID 26411452, 2016). "MBC is a hormone-driven tumor and steroid receptors, namely the estrogen receptor (ER), progesterone receptor (PgR) and androgen receptor (AR) are often expressed." (PMID 27248471, 2016). "In conclusion, utilizing HTM/HCA, we have identified the Bisphenol A analog, BPAP, as a novel molecule capable of reducing the levels of AR (both full-length and variants) in CRPC tumor cell models in vitro." (PMID 26918604, 2016).
tumor (continued). "Preclinical studies have shown that AR inhibits ER activity by blocking it's downstream transcription targets, thus inhibiting ER-stimulated tumor growth in ER-positive cell lines." (PMID 27285752, 2016). "Our data examined AR expression in metastatic lesions for the first time, and demonstrated significantly higher AR expression than in the matched primary tumours." (PMID 26930451, 2016). "First, AR suppresses CD90 expression in primary tumors partially by upregulating HIS3H2A, which consequently results in a reduction in CD90+ tumor cell populations in the blood, thereby reducing the risk of recurrence." (PMID 27340775, 2016). "Several in vitro and in vivo studies have already shown that decitabine can effectively inhibit PCa cell and control tumor growth 29, 30, but have mostly concentrated on pathways related to the androgen receptor (AR)." (PMID 27198154, 2016). "The findings also demonstrate that AR expression in CTCs and primary tumor tissue is correlated with postoperative recurrence of HCC, in an opposite pattern." (PMID 27340775, 2016). "Our study identifies novel cooperative mechanisms involving PIP5K1α, AR-V7, CDK1 and AR, which drive tumor progression and contribute to enzalutamide resistance." (PMID 27588408, 2016). "If that is the case, when patients receive ADT, BC recurrence is induced by other pathways that are more dominant in AR-negative tumor compared with AR-positive tumor." (PMID 26885620, 2016). "By maintaining an androgenic gene signature, AR-Vs drive tumour survival and progression in castrate conditions." (PMID 26336819, 2015). "It is commonly accepted that NE tumor cells are AR- and PSA-negative and prostatic acid phosphatase-positive [Ref." (PMID 25785244, 2015). "Mechanisms driving CRPC are highly complex and diverse, and there is evidence for genetic differences across different populations and numerous oncogenes and tumour suppressors are active in CRPC bypassing AR signalling." (PMID 26553226, 2015). "Recently, a number of tumor intrinsic ENZ resistance mechanisms dependent on the AR have been identified in metastatic CRPC, but differences in immune responses in these patients were outside the scope of this work." (PMID 25428917, 2015). "We conclude that catalytic Topo II inhibitors can block AR signaling and inhibit tumor growth of CRPC xenografts, identifying a potential co-targeting approach using these inhibitors in combination with AR pathway inhibitors in CRPC." (PMID 26009876, 2015). "Crucially, CRPC tumours remain dependent upon AR signalling; exemplified in both androgen sensitive (AS) and CRPC cells where decreased AR expression induces a concomitant loss of cell viability." (PMID 26448047, 2015). "Stromal AR seems essential for epithelial proliferation control and is able to modulate the surrounding tumor promoting microenvironment." (PMID 25793207, 2015). "Initially, the reduction of circulating androgens decreases androgen receptor (AR)-mediated proliferation and survival of tumor cells." (PMID 26325261, 2015). "The continual accrual of genomic aberration together with the de-differentiating force of sustained AR inhibition provides opportunities for tumour cells to escape dependence on AR signalling." (PMID 25896606, 2015). "The observed enhanced resistance to AR inhibitors in response to PMEPA1 depletion was consistent with the observed castration resistance of PMEPA1shRNA harboring tumor xenografts." (PMID 25883222, 2015). "We found that the major factor of the tumor immunophenotype variation was characterized by a strong inverse relation between the expression of ER, PR, AR along with anti-apoptotic marker BCL2, on one side, and Ki67 and HIF-1α, on the other side." (PMID 26512778, 2015).